ZSCAN10 (zinc finger and SCAN domain containing 10)
Description:
Embryonic stem (ES) cell-specific transcription factor required to maintain ES cell pluripotency. Can both activate and /or repress expression of target genes, depending on the context. Specifically binds the 5'-[GA]CGCNNGCG[CT]-3' DNA consensus sequence. Regulates expression of POU5F1/OCT4, ZSCAN4 and ALYREF/THOC4.
Synonyms: ZNF206; OFNS; ZFP206
Tractability: No criterion of Open Targets' tractability assessment is met for any kind of drug.
Gene: Protein-coding gene on chromosome 16 (3,088,890 to 3,099,295, reverse strand). Ensembl gene ENSG00000130182.
Subcellular location: Nucleus
Subcellular location (Human Protein Atlas): Nucleoplasm; Centrosome
Pathways (Reactome):
Developmental Biology: Transcriptional regulation of pluripotent stem cells
Gene Ontology:
Molecular function: protein binding; DNA-binding transcription factor activity; DNA-binding transcription factor activity, RNA polymerase II-specific; RNA polymerase II cis-regulatory region sequence-specific DNA binding; sequence-specific DNA binding
Biological process: negative regulation of DNA-templated transcription; regulation of transcription by RNA polymerase II
Cellular component: nucleus; nucleoplasm
Genetic constraint (gnomAD): Loss-of-function variants: 52 observed, 49.95 expected, observed/expected ratio (o/e) 1.04, 90% interval 0.83 to 1.31. The synonymous counts are far from expectation, so gnomAD's model fits this gene poorly and the ratio says little. Missense variants: 1,223 observed, 1,007.7 expected, observed/expected ratio (o/e) 1.21, 90% interval 1.16 to 1.27. Synonymous variants: 544 observed, 432.13 expected, observed/expected ratio (o/e) 1.26, 90% interval 1.17 to 1.35.
Homologues: Orthologues: chimpanzee ZSCAN10 (99% identical), macaque ZSCAN10 (97% identical), pig ZSCAN10 (80% identical), dog ZSCAN10 (78% identical), guinea pig ZSCAN10 (75% identical), mouse Zscan10 (72% identical), rat Zscan10 (70% identical), rabbit ZSCAN10 (61% identical). Paralogues in human: ZNF658 (30% identical), ZNF33B (29% identical), ZNF568 (29% identical), ZNF585B (28% identical), ZNF189 (28% identical), ZNF235 (28% identical), ZNF311 (27% identical), ZNF226 (27% identical), ZNF227 (27% identical), ZNF234 (27% identical), ZNF250 (27% identical), ZNF16 (27% identical), and 164 more.
Diseases named in the same sentence as ZSCAN10 in open-access papers:
ZSCAN10 is named in the same sentence as 7 diseases in open-access papers, as found by Europe PMC text mining. Sharing a sentence is not in itself a finding about the gene and the disease. The quoted sentences say what the papers report.
Anxiety (1 paper, 2014). Intense feelings of nervousness, tension, or panic often arise in response to interpersonal stresses. "However, female Zscan10 homozygous mutants also show an increased acoustic startle response, which is not consistent with the notion of reduced anxiety, and demonstrated a functional visual impairment in the optokinetic drum test." (PMID 25111779, 2014).
Cognitive impairment (1 paper, 2024). Abnormal cognition is characterized by deficits in thinking, reasoning, or remembering. "Although the expression of ZSCAN10 decreases in the later stages of human embryonic development, residual expression in the brain and testis may be associated with phenotypic features that include cognitive impairment and, in some cases, microgenitalia and maldescended testis." (PMID 38386308, 2024).
developmental delay (1 paper, 2025). "Biallelic ZSCAN10 loss-of-function variants were identified in seven affected individuals who consistently reported global developmental delay, facial asymmetry and malformations of the outer ear." (PMID 41191133, 2025).
seminoma (1 paper, 2025). A radiosensitive malignant germ cell tumor found in the testis (especially undescended), and extragonadal sites (anterior mediastinum and pineal gland). "Another study in seminomas indicates that the overexpression of PRAME and its interaction with Lin28A support pluripotency networks and expression of reprogramming markers, such as DPPA3, Nanog, Oct3/4, ZSCAN10, and PRDM14." (PMID 40961095, 2025).
neurodevelopmental disorder (1 paper, 2024). A behavioral and cognitive disorder with onset during the developmental period that involves impaired or aberrant development of intellectual, motor, or social functions. "Our findings provide evidence of a novel syndromic neurodevelopmental disorder caused by bi-allelic loss-of-function variants in ZSCAN10." (PMID 38386308, 2024). "The identification of four different bi-allelic PTVs in ZSCAN10 in seven affected members of five families establishes ZSCAN10 as a gene confidently implicated in this syndromic neurodevelopmental disorder." (PMID 38386308, 2024).
ZSCAN10 also shares sentences with these, for which no sentence is quoted: CHARGE syndrome (1 paper); genetic disorders (1).